CRP (C-reactive protein)
Diseases named in the same sentence as CRP in open-access papers (continued):
Sharing a sentence is not in itself a finding about the gene and the disease.
infection (continued). "A known trigger of elevated CRP levels is infection, which is also evident from our data, since infection as a main diagnosis is a strong predictor of admission CRP concentration." (PMID 40275239, 2025). "Disruptions in lipoproteins, cholesterol, and fatty acids observedduring severe infection were significantly restored during the postinfectionstage, as well as severity marker proteins such as CRP, SAA1, andSERPINA3." (PMID 40997940, 2025). "The small number of clinically mild false negatives suggests that a CRP-first approach is safe only when integrated with clinical review: imaging should still proceed if pain persists, infection is suspected or examination findings are concerning." (PMID 41204018, 2025). "With a few exceptions, all patients with elevated CRP (usually values > 2 mg/dL) values were subjected to an infectious disease focus search preoperatively, and any infection found was treated." (PMID 40001448, 2025). "C-reactive protein has been shown to distinguish infection from colonization in A. baumannii and predict death from this and other pathogens." (PMID 39601576, 2025). "The C-reactive protein(CRP)/albumin ratio represents a combination of the infection level andnutritional status." (PMID 40622101, 2025). "The median lactate level at the time of infection diagnosis showed a slight decrease compared to the median at the time of the burn, while the median CRP level at infection was higher than at the time of the burn." (PMID 40802437, 2025). "This criterion can be based on the presence of acute or chronic disease, infection, or injury, but the management of C-reactive protein (CRP) as a key biomarker can be used when inflammatory components are uncertain." (PMID 40431361, 2025). "Here we investigated the association between serial CRP percentile changes, antibiotic prescribing patterns, and patient outcomes in a large cohort with suspected infection, acknowledging that CRP is one of multiple factors in clinical decision-making." (PMID 40764898, 2025). "In septic neonates not on MCS, both Presepsin and sTREM-1 were significantly elevated compared to non-septic neonates and these biomarkers had greater sensitivity and specificity compared to CRP in detecting infection." (PMID 40523137, 2025). "The multivariate analysis for death at 90 days included variables with p < 0.20: age, gender, neoplasm, anticoagulation, mechanical ventilation, steroids, superimposed infection, dialysis, and C reactive protein." (PMID 39792860, 2025). "Physicians have probably used similar parameters, such as CRP or temperature, to diagnose infection." (PMID 38963607, 2025). "The primary objective of this systematic review was to evaluate the diagnostic accuracy of CRP, PCT, and WBC count in detecting early post-surgical infections across various surgical disciplines." (PMID 40342430, 2025). "The objective of this work is to investigate the predictive value of the neutrophil-to-lymphocyte ratio (NLR) combined with the C-reactive protein/albumin (CRP/ALB) ratio for postoperative infections in patients undergoing spinal surgery." (PMID 41019129, 2025). "Acute inflammation or infection is related to a specific protein type called C-reactive protein (CRP)." (PMID 40047848, 2025). "CRP, rather, should be used as a screening tool for ongoing infections pre- and postoperatively to initiate adequate treatment to reduce the risk of hematogenous PJI." (PMID 40001448, 2025). "It is practically and ethically unfeasible to blind clinicians to CRP in the decision to investigate or treat for a presumed infection in current practice." (PMID 40319081, 2025). "On workup, he was found to have elevated blood glucose levels at 141 mg/dL, a total count of 13,000 /μL with 70.8% polymorphs, ESR of 45 mm/first hour, C-reactive protein (CRP) 94.3 mg/L, and procalcitonin of 0.16 ng/mL, suggestive of infection." (PMID 40385788, 2025).
infection (continued). "Utilising point-of-care testing (PoCT) for indicators of infection, such as C-reactive protein (CRP), is also an intervention with evidence of providing clinical decision-support and reducing antibiotic prescribing." (PMID 41009893, 2025). "CRP is a widely recognized acute-phase reactant synthesized by the liver in response to systemic inflammation and infection." (PMID 40310418, 2025). "When detecting infection in the body, CRP and ESR are highly sensitive and regarded as useful screening tests, but they carry the disadvantage of low specificity." (PMID 40565991, 2025). "C-reactive protein (CRP) is an acute-phase protein predominantly synthesized by the liver in response to cytokine signaling at sites of tissue injury or infection." (PMID 41281572, 2025). "Baseline covariates for matching were the microorganism (likely or not likely to be a contaminant), patient demographics, joint, revision type, surgical site infection score, American Society of Anesthesiologists classification, serum C-reactive protein (CRP)." (PMID 40114987, 2025). "Other top-ranking features—CRP, NLR, and SII—highlighted the role of inflammatory and nutritional disturbances, underscoring the importance of immune-nutritional status in infection risk." (PMID 41459072, 2025). "CRP, a widely used marker of inflammation, increases rapidly in response to infection, making it a reliable indicator of the body’s inflammatory status." (PMID 40584620, 2025). "After 14 days of targeted antibiotic therapy, the patient's condition improved, with a return to normal body temperature and normalization of infection parameters, including C-reactive protein and procalcitonin." (PMID 41487767, 2025). "Qualitative studies have shown that CRP tests are employed to distinguish between viruses and bacteria, assess the severity of the infection, guide antibiotic prescribing and communicate this assessment with the patient." (PMID 39460385, 2025). "These patients presented significantly elevated CRP and neutrophil levels, indicating an inflammatory response consistent with the acute phase of infection." (PMID 39998323, 2025). "Its role in monitoring infection and recovery is more controversial, but is of interest when combined with clinical status and inflammatory markers such as CRP to guide the discontinuation of antibiotic therapy." (PMID 39861912, 2025). "The existing literature has almost exclusively investigated the accuracy of serum CRP levels in the diagnosis of a suspected infection, which is beyond the scope of our study." (PMID 40565868, 2025). "Serial CRP measurements are frequently requested by clinicians aiming to assess recovery from infections and tailor treatment accordingly, including in BSI." (PMID 40764898, 2025). "Due to a mild fever and elevated C-reactive protein levels, a PCR test confirmed an infection with the AH3+ influenza virus." (PMID 41573196, 2025). "Initial hematological and biochemical parameters obtained upon admission to the hospital included a complete blood count, renal function tests, and infection markers such as C-reactive protein and procalcitonin." (PMID 41487767, 2025). "In the multiple regression analysis, PCT, CRP, and lactate retained their significance for the diagnosis of infection." (PMID 40521830, 2025). "To better understand the role of CRP in melioidosis, we conducted a systematic review and meta-analysis of observational studies that reported CRP levels in patients with confirmed infection." (PMID 41010302, 2025). "In contrast to SAA detection, CRP, an established biomarker of infection, presented with a surprisingly low sensitivity of only 37% (31%, 42%) at 95% CI." (PMID 39937751, 2025). "In all animals except Subject 01, C-reactive protein was elevated by 1 dpi, consistent with acute systemic inflammation brought on by infection with SARS-CoV-2." (PMID 41157643, 2025).
infection (continued). "Widely utilized in clinical settings, CRP serves as a crucial indicator for assessing the presence and severity of infection or systemic inflammation." (PMID 40277527, 2025). "These included local edema, ESR/CRP elevation, post-operative infection, post-operative bleeding, tissue ischemia, and mortality." (PMID 41001471, 2025). "Complement activation by ligand-complexed CRP is necessary for CRP-mediated protection against infection." (PMID 40740789, 2025). "Recently, CAR was proven to be not only a better diagnostic marker for PJI than CRP and ESR, but also a useful biomarker for predicting surgical site infection after major abdominal surgery." (PMID 41488484, 2025). "As a central mediator of the acute-phase response, IL-6 promotes CRP synthesis in hepatocytes, enhances neutrophil activation, and regulates the early inflammatory cascade by mobilizing immune cells to the site of infection." (PMID 41018059, 2025). "During hospitalization, infection-related indicators (white blood cell count, C-reactive protein, procalcitonin, and interleukin-6) all returned to normal ranges, and body temperature remained stable." (PMID 40980129, 2025). "This is in line with previous research concluding that CRP is of limited value in detection of infection, at least until 3–5 days after surgery." (PMID 40439832, 2025). "As we observed a correlation between CRP spikes and B-cell depletion, B-cell depleted patients were also overall more likely to die from late infections." (PMID 39562716, 2025). "In all of our cases, MRI showed typical infection signals in the intervertebral space, with elevated CRP and ESR levels, and some cases had an increased WBC." (PMID 40458520, 2025). "Accordingly, the present study aimed to evaluate the therapeutic potential of exosomes isolated from a bovine spleen leukocyte extract (IMMUNEPOTENT CRP), loaded with gentamicin, in reducing infection and accelerating wound repair in a diabetic mouse model." (PMID 41394149, 2025). "Patients in the infection group had lower platelet counts, higher CRP levels, more critical cases, and poorer prognosis." (PMID 41355980, 2025). "CRP is an acute-phase protein produced by the liver in response to inflammation, infection, or tissue injury, making it a reliable marker of systemic inflammation." (PMID 40407554, 2025). "Among these patients, 37 also had inflammatory indicators, such as C-reactive protein (CRP) and procalcitonin (PCT), which reflect the state of the body after infection to varying degrees, and the average CRP and PCT levels were 43.5 and 2.6, respectively." (PMID 41299356, 2025). "Previous pediatric studies have shown mixed results regarding the predictive value of CRP and Procalcitonin for new infection during MCS." (PMID 40523137, 2025). "CRP is produced as a response to an infection or trauma, upregulated by cytokines, especially IL-6, but also IL-1 and TNF." (PMID 41007875, 2025). "As infection and elevated inflammation markers like CRP or leucocyte count usually correlate with each other, in these analyses, none of the selected factors was statistically independently relevant for survival after surgery." (PMID 39762956, 2025). "The score includes using an initial lab CRP, an easily accessible, extensively studied and inexpensive biomarker for infection." (PMID 39838378, 2025). "In the context of infection diagnostics, this means outperforming established markers such as CRP and PCT, which are inexpensive, readily available, and often considered ‘good enough’ for continued clinical use." (PMID 41149760, 2025). "CRP is one of the most commonly used biomarkers to monitor inflammation and possible infection after surgery." (PMID 41153812, 2025). "A persistently elevated CRP or a second rise in CRP levels after the expected peak has been identified as a warning sign of postoperative infection in several studies." (PMID 41153812, 2025).
infection (continued). "This was suggested by the PMN infiltrates into the infection site, adhesions under the fascia, necrotic and friable tissue, and elevated systemic numbers of white blood cells and C-reactive protein." (PMID 41244318, 2025). "CRP, an acute-phase protein, significantly increases during infection or tissue damage and enhances complement activation and macrophage phagocytosis to clear pathogens and damaged cells." (PMID 40565944, 2025). "In contrast, only 2 patients with confirmed SSI demonstrated a rising CRP trend in the early postoperative period, indicating poor sensitivity of this marker for early infection detection." (PMID 41226908, 2025). "Chronic ulcers that persist despite treatment often demonstrate ongoing inflammation, recurrent infection, and tissue necrosis, which contribute to elevated CRP levels and poor healing potential." (PMID 41367458, 2025). "Elevated CRP levels often reflect an acute-phase response to tissue injury, systemic inflammation, or infection, and persistently high postoperative CRP levels can indicate an increased risk for the development of ICI." (PMID 40529435, 2025). "In autoimmune ECM- and hydrogel-treated patients, traumatic injury had reduced odds of ESR/CRP elevation, wound dehiscence, and post-operative infection." (PMID 41001471, 2025). "Strains such as Lactobacillus acidophilus and Bifidobacterium longum have demonstrated efficacy in reducing CRP levels, lowering infection risks, and promoting recovery." (PMID 40431221, 2025). "PCT responds to infection faster than CRP and begins to increase at 4 h after infection and peaks at 12–24 h." (PMID 39886481, 2025). "Mouse CRP shares 71% amino acid homology with the human ortholog, but is stably expressed at low levels even under infection conditions." (PMID 41214213, 2025). "Premature infants had lower CRP levels, with a rise of 0.405 mg/l for every one-week increase in gestational age, and a slight rise was noted during infection." (PMID 40970024, 2025). "The cutoff value for the CRP level at admission was found to be ≥6.74 mg/dL for predicting the presence of infections that would hinder chemotherapy in all patients." (PMID 40125102, 2025). "Where comparator data were available, CRP levels in melioidosis were consistently higher than in other infections." (PMID 41010302, 2025). "The current literature almost exclusively focuses on human CRP, primarily due to the massive induction in response to infections and inflammation." (PMID 41214213, 2025). "In general, elevated CRP is a marker of infection which significantly impairs wound healing in diabetic patients with CLTI." (PMID 40660298, 2025). "During the treatment period, it is essential to closely monitor the patient’s blood routine, infection indicators (such as C-reactive protein and blood cultures), and clinical manifestations to promptly detect signs of infection." (PMID 40176885, 2025). "All patients in this study received empiric antibiotic therapy before biomarker sampling, in line with current clinical practice guidelines and because initial suspicion of infection was supported by elevated CRP and/or leukocyte counts." (PMID 41354872, 2025). "The most studied non-specific acute-phase protein in COPD exacerbations is C-reactive protein (CRP), which can serve as a biomarker for infection." (PMID 39860403, 2025). "Persistently elevated CRP often indicates inadequate infection control or the presence of complications." (PMID 41291834, 2025). "ECMO alters the host’s immune response, which complicates the interpretation of classic infection markers such as fever, leukocytosis, C-reactive protein (CRP), and procalcitonin (PCT)." (PMID 41009912, 2025). "Results were consistent between analyses using the imputed sample and complete case sample and the sample excluding individuals with CRP >10 mg/L or reporting infection at the time of blood collection." (PMID 40814293, 2025).
infection (continued). "For bacterial mono-infections, the only abnormal finding was in the CRP levels, which had a mean value CRP of 93 ± 99 mg/L." (PMID 41210881, 2025). "Inflammatory markers (CRP, ESR, WBC) were substantially elevated and highly variable, suggesting pronounced systemic inflammation and possible underlying infection." (PMID 41374452, 2025). "In severe inflammation, CRP levels can rise over a thousandfold, directly correlating with the severity of infection and injury." (PMID 39717869, 2024). "A systematic review and meta-analysis found that CRP measured in a laboratory is one of the best biomarkers currently available to identify severe infections in children." (PMID 38504318, 2024). "Although direct causal relationships between inflammatory biomarkers and anti-HAV and anti-HBV antibody levels are difficult to establish, CRP monitoring post-infection is valuable for tracking inflammation." (PMID 39205303, 2024). "CRP values greater than 180 mg/dL on day 3 and 140 mg/dL on day four served as a threshold of post-operative infections in both surgical approaches." (PMID 38184537, 2024). "Inflammatory markers like WBC count and CRP concentration are routinely employed to ascertain the presence of an active infection or inflammatory condition." (PMID 39020267, 2024). "Higher levels of the inflammatory blood markers WBC (white blood cell) count and CRP in the latter two subgroups compared to SIRS agreed with the presence of infection." (PMID 39434093, 2024). "CRP is an acute phase reactant that is released in the process of inflammation during infection with various infectious agents, including infection with various viruses." (PMID 39064460, 2024). "In our study, serum OPG was significantly correlated to all three known indices of infection (CRP, ESR, and WBC) with the strongest correlation to CRP." (PMID 38509997, 2024). "In comparison to other values, PCT appears to become elevated much earlier in the disease course (peak at two hours versus five for CRP) and decreases quicker after the resolution of the infection." (PMID 38975447, 2024). "Despite the presumption of increases in CRP values in cases of infection, these values persist below the baseline." (PMID 39120214, 2024). "C-reactive protein (CRP) is an acute-phase reactive protein, and its levels are usually elevated in the presence of inflammation, infection, or tissue damage in the body." (PMID 39902040, 2024). "Serum micronutrient biomarkers will be adjusted for inflammation and infection using C-reactive protein (CRP) and alpha 1-acid glycoprotein (AGP)." (PMID 38448918, 2024). "The laboratory investigation showed signs of infection (leukocytosis, high levels of c-reactive protein)." (PMID 38400177, 2024). "Both infection and rheumatologic groups showed significantly higher maximum CRP levels than the immune dysregulation group (P = 0.037, P = 0.047 respectively)." (PMID 39264477, 2024). "C-reactive protein (CRP) is a major acute-phase protein that rapidly increases in plasma during infections or tissue damage." (PMID 39717869, 2024). "CRP, a commonly used marker for inflammation, elevated CRP levels post-surgery often implies presence of infection or inflammation." (PMID 39054495, 2024). "CRP plays one of the most important roles in the immune system by modulating the inflammatory response and promoting host defense against infections." (PMID 38891863, 2024). "CRP levels generally peaked 1–2 days after blood culture collection, with varying responses for different pathogens and infection sources (p < 0.0001)." (PMID 38599549, 2024). "While CRP is a marker of acute infection and metabolic inflammation, suPAR is a marker of cellular inflammation and subclinical organ damage." (PMID 39457043, 2024). "Elevated levels of WBCs, CRP, and PCT in the deceased group indicate an exaggerated immune response associated with severe infections." (PMID 39202627, 2024).